BCAR1 (BCAR1 scaffold protein, Cas family member)
Diseases named in the same sentence as BCAR1 in open-access papers (continued):
Sharing a sentence is not in itself a finding about the gene and the disease.
breast carcinoma (continued). "In this work, we elaborated the enhancement effect of a novel carcinogenetic molecule, ie, p130cas (breast cancer antiestrogen resistance 1, BCAR1) on proliferation and cell growth of lung cancer cells,and to explore the possible networks of interacting proteins of BCAR1." (PMID 33001583, 2020). "In conclusion, the BCAR1 and BCAR3 interaction triggers a comprehensive signaling cascade that culminates in anti-estrogen resistance in breast cancer cells." (PMID 38730626, 2024). "In the present research, we identified 3 RNAs (hsa-miR-105-5p, BCAR1 and PANX2) might associated with prognosis and metastasis of breast cancer, which might be provide a new perspective for metastasis of breast cancer and contributed to the treatment of breast cancer." (PMID 34055638, 2021). "In this review, a synopsis of 15 years of research on the role of p130Cas/BCAR1 and p140Cap/SRCIN1 in breast cancer will be presented." (PMID 34708040, 2021). "Inversely, breast cancer patients with higher expression level of AHRR, ANKRD52, BCAR1, PANX2, hsa-miR-105-5p, hsa-miR-4435, and LINC01742 showed the lower OS." (PMID 34055638, 2021). "The enhancer function of SOD2 in cellular migration and metastasis is further supported by data demonstrating the correlation of SOD2 expression and phosphorylation of breast cancer anti-estrogen resistance protein 1 (BCAR1), also known as p130Cas." (PMID 29478325, 2019). "FAK induces BCAR1 (breast cancer anti-estrogen resistance 1) and MAPK8 mediated cellular motility, proliferation, and survival in breast cancer." (PMID 35582722, 2019). "To verify the involvement of p130Cas (BCAR1) in PKN3‐induced cancer progression, we performed a set of experiments with MDA‐MB‐231 breast cancer cells." (PMID 30422386, 2019). "BCAR1 forms a phosphorylation-dependent signaling complex with FAK and Src kinase, promoting the adhesion-mediated breast cancer survival rate." (PMID 25502723, 2015). "Like p130Cas/BCAR1, Nedd9 is strongly over-expressed in human breast cancers with respect to normal tissue." (PMID 25606587, 2014). "Noteworthy, in spite of their structural similarity, p130Cas/BCAR1 and Nedd9 exert both redundant and specific functions in breast cancer cells." (PMID 25606587, 2014). "Both p130Cas/BCAR1 and Nedd9 are abundantly expressed in human breast tumours and breast cancer cell lines." (PMID 25606587, 2014). "Significantly we found that silencing of BCAR1, a proposed downstream mediator of TNK2, inhibits breast cancer cell invasion via a mechanism distinct from the EGFR." (PMID 18435854, 2008). "Consistent with previously characterized tumor-promoting properties of BCAR3, particularly BCAR3 critical role as an activator of p130Cas/BCAR1-dependent cell motility, we observed a pivotal function for K334me1 of BCAR3 in controlling breast cancer migration and metastasis." (PMID 38296970, 2024). "Finally, further analysis is needed of both BCAR1 and SRCIN1 gene status and regulation in specific breast cancer subtypes, in order to address their real contribution to the biological heterogeneity of human tumors in terms of patient stratification." (PMID 34708040, 2021). "Moreover, ICAM3, CCL16, PDE3A, PRTN3, TRAF6, BCAR1, IL-1α, IL-1β, NFκB1, SOX2 and OCT4 decreases the protein expression as indicated by immunofluorescence staining in the ibuprofen-treated MDA-MB-231 breast cancer cells versus the control." (PMID 32528119, 2020). "It is reported that in breast cancer cells, overexpression of BCAR1 increases c-Src kinase activity and modulates non-genomic estrogen signaling." (PMID 30683095, 2019). "Other downregulated genes, including breast cancer anti-estrogen resistance protein 1 (BCAR1, also known as p130Cas) and SHC adaptor proteins 3 and 4 (SHC3, SHC4), are key players in the regulation of cell migration by acting as scaffolds for tyrosine kinase-related signaling." (PMID 30086712, 2018).
breast carcinoma (continued). "To confirm differential gene expression levels in the three breast cancer subtypes, Her2+, ER + and TNBC, we selected 6 genes (ITGA3, ITGA5, OXTR, WNT5B, BCAR1, FZD1) with significantly different levels of expression based on our microarray studies and validated their expression levels by qRT-PCR." (PMID 22954256, 2012). "We also show here that BCAR1 siRNA silencing can function to inhibit invasion of breast cancer cells, even when the cells were not transfected with constitutively activated Cdc42 as was previously demonstrated." (PMID 18435854, 2008). "The BCAR1 and BCAR3 genes both encode components of intracellular signal transduction, but their direct effect on breast cancer cell proliferation is not known." (PMID 15642172, 2005). "Additionally, in Luminal A and B breast cancer subtypes, low BCAR3 expression, alongside BCAR1, correlates with poor prognosis, adverse lymph node status, and diminished response to hormonal therapy, indicating potential as markers for endocrine therapy resistance." (PMID 38730626, 2024). "To date, several signalling pathways relevant to breast cancer aetiology, including transforming growth factor (TGF)-beta, progesterone and hypoxia signalling, have been found to positively regulate Nedd9 mRNA expression, but less is known about the transcriptional control of p130Cas/BCAR1." (PMID 25606587, 2014).
lung carcinoma (13 papers, 2012 to 2025). "Our previous research demonstrated that high expression of BCAR1 in lung cancer promotes EMT, invasion, and metastasis of tumor cells, and it also predicts poorer prognosis in lung adenocarcinoma cases." (PMID 33001583, 2020). "Fortunately, we obtained four hub genes (MAPK3, MOV10, XAB2, and POLR2A), which potentially interact with BCAR1 and play carcinogenetic roles in lung cancer." (PMID 33001583, 2020). "High expression of POLR2A was significantly positively correlated to BCAR1 overexpression and predicted poor prognosis in 54 lung cancer cases." (PMID 33001583, 2020). "Cell growth arrest, inhibition of cell migration, and EMT can occur following BCAR1‐KO in lung cancer cells." (PMID 33001583, 2020). "POLR2A and BCAR1 were significantly increased in lung cancer tissues as compared with matched normal tissues." (PMID 33001583, 2020). "High expression of either BCAR1 or POLR2A predicted poor prognosis in 54 lung cancer cases in early stage." (PMID 33001583, 2020). "Moreover, synergism analysis is needed to demonstrate the role of interaction between BCAR1 and its partners with respect to proliferation and cell growth in lung cancer." (PMID 33001583, 2020). "Furthermore, the networks of proteins that interact with BCAR1 to trigger the proliferation of lung cancer cells remain to be identified." (PMID 33001583, 2020). "Furthermore, our previous studies indicated serum BCAR1 levels were significantly higher in lung cancer compared with the control group, gradually increasing with the progression of tumor staging, and decreasing following malignant lesion removal." (PMID 28423562, 2017). "Furthermore, BCAR1 is found to be highly expressed in lung cancer cell lines." (PMID 33001583, 2020). "Moreover, BCAR1 has been considered as a new potential molecular marker for lung cancer." (PMID 33001583, 2020). "Thus far, very few studies focused on the carcinogenesis of BCAR1 in lung cancer." (PMID 22558353, 2012). "Besides, BCAR1 is known as Src substrate, and Src inhibitor AZD0530 can also result in significant inhibition of cell migration and matrigel invasion in lung cancer cells, which potentially supports the carcinogenesis of Src/BCAR1 axis." (PMID 22558353, 2012). "However, to our knowledge, no study has previously investigated the role of BCAR1 in lung cancer cell proliferation." (PMID 33001583, 2020). "Based on these findings, we speculate that BCAR1 can, at the very least, indirectly upregulate POLR2A expression, which has critical biological functions leading to cell proliferation, cell growth, and subsequent poor prognosis in lung cancer cases." (PMID 33001583, 2020).
prostate carcinoma (12 papers, 2011 to 2025). A carcinoma that arises from epithelial cells of the prostate gland. "Initial evidence also suggests a role for BCAR1 in prostate cancer progression, as its overexpression was linked to an unfavorable tumor phenotype and biochemical relapse in three studies analyzing 110, 130 and 242 prostate cancer specimens." (PMID 29304771, 2018). "The results of our study identify BCAR1 as a prognostic biomarker with potential clinical value for risk stratification of ERG-negative prostate cancer." (PMID 29304771, 2018). "To evaluate whether BCAR1 expression is associated with ERG rearrangements in prostate cancers, we used pre-existing data on ERG status obtained by FISH in 5379 cancers and by IHC in 8421 tumors for which BCAR1 staining was also available." (PMID 29304771, 2018). "Previous studies showed positive correlation between PKN3 or p130Cas (BCAR1) protein levels and cancer progression in patients with breast or prostate cancer." (PMID 30422386, 2019). "In cancer cells, cytoplasmic BCAR1 expression was observed in 77.6% of 9472 interpretable prostate cancers; weak in 15.9%, moderate in 23.2%, and strong in 38.5% of cases." (PMID 29304771, 2018). "These numbers fit well to previous TMA based studies, which reported up to 90% of BCAR1 positivity in sets of 110 up to 242 prostate carcinomas." (PMID 29304771, 2018). "Based on these data, we intended to confirm the biologic and prognostic role of BCAR1 protein in a very large cohort of prostate cancer patients." (PMID 29304771, 2018). "The level of BCAR1 staining was associated with the presence of ERG rearrangements and ERG expression in prostate cancers (p < 0.0001 each)." (PMID 29304771, 2018). "To understand the effect of BCAR1 in prostate cancer, we analyzed its expression on more than 11,000 prostate cancer samples." (PMID 29304771, 2018). "The analysis revealed cytoplasmic BCAR1 staining in 76.6% of 9495 analyzable prostate cancers." (PMID 29304771, 2018). "Thus the BCAR1 biomarker may best aid in decision making if combined with other marker in ERG-negative prostate cancer." (PMID 29304771, 2018). "ERG does not seem to be implicated in transcriptional control of BCAR1 based on the results of studies analyzing global transcriptional changes between ERG-negative and ERG-positive prostate cancers." (PMID 29304771, 2018). "However, BCAR1 may be a useful marker if combined with other molecular markers, especially for ERG-negative prostate cancer." (PMID 29304771, 2018). "Consistent with earlier findings, BCAR1 staining was barely detectable in luminal cells of non-neoplastic prostatic glands but clearly up regulated in a large fraction of prostate cancers, which suggests a role for BCAR1 during prostate cancer development." (PMID 29304771, 2018).
breast tumors (9 papers, 2008 to 2021). "It has been established that patients with primary breast tumours expressing a high level of p130Cas/BCAR1 protein, experience more rapid disease recurrence and are at a higher risk for intrinsic resistance to tamoxifen therapy." (PMID 18475297, 2008). "Moreover, it has been shown that patients with primary breast tumors expressing high levels of p130Cas (also known as BCAR-1) experience a more rapid disease recurrence and have a greater risk of resistance to tamoxifen therapy." (PMID 23239970, 2012).
lung adenocarcinoma (8 papers, 2012 to 2025). A carcinoma that arises from the lung and is characterized by the presence of malignant glandular epithelial cells. "Herein, we aimed to determine the role of BCAR1 in proliferation and cell growth in lung adenocarcinoma, on which few studies have previously focused." (PMID 33001583, 2020). "POLR2A and BCAR1 were significantly increased in lung adenocarcinoma tissues compared to adjacent normal tissues (1.090 ± 0.082 vs. 0.746 ± 0.236, P < 0.05 and 0.810 ± 0.090 vs. 0.589 ± 0.156, P < 0.05, respectively)." (PMID 33001583, 2020). "This study was designed to investigate the effects of a novel carcinogenetic molecule, p130cas (breast cancer antiestrogen resistance protein 1 or BCAR1) on proliferation and cell growth in lung adenocarcinoma." (PMID 33001583, 2020). "And we verified the carcinogenic roles of BCAR1 via RNA interference (RNAi) in A549 lung adenocarcinoma cell line." (PMID 22558353, 2012). "Herein, we aim to evaluate the predictive power of BCAR1 as a marker for poor prognosis in NSCLC cases, verify the carcinogenic roles of BCAR1 in the A549 lung adenocarcinoma cell line, and testify to the BCAR1/phospho-p38 axis." (PMID 22558353, 2012). "Herein, we chose to study preclinical and clinical implications of BCAR1 in lung adenocarcinoma." (PMID 33001583, 2020). "In lung adenocarcinoma, POLR2A expression strongly correlates with BCAR1 (breast cancer antiestrogen resistance protein 1) overexpression and with unfavorable clinical outcomes." (PMID 41487511, 2025). "First, we evaluated proliferation, cell colony formation, apoptosis, and cell cycle after BCAR1 was knocked out (KO) using CRISPR‐Cas9 technology in H1975 and H1299 human lung adenocarcinoma cells." (PMID 33001583, 2020). "Ultimately, we validated the correlated expressions of BCAR1 and a selected hub gene, RNA polymerase II subunit A (POLR2A), in 54 lung adenocarcinoma tissues, as well as in H1975 and H1299 cells." (PMID 33001583, 2020). "This suggests a regulatory interaction between BCAR1 and RPB1 that may contribute to the aggressive behavior of lung adenocarcinoma." (PMID 41487511, 2025). "Intriguingly, BCAR1‐KO in lung adenocarcinoma cell lines had no impact on the cell cycle." (PMID 33001583, 2020).
colorectal cancer (7 papers, 2017 to 2025). A primary or metastatic malignant neoplasm that affects the colon or rectum. "BCAR1 is an inflammatory gene that has been shown to be a novel biomarker for colorectal cancer prognosis." (PMID 32812032, 2020). "Furthermore, the BCAR1/Rac1 axis can suppress colorectal cancer and metastasis through the Hippo, ERK, and PAK signaling pathways 38, indicating the signaling pathway is indispensable in cell signal transduction." (PMID 34326687, 2021).
ovarian carcinoma (7 papers, 2015 to 2025). A malignant neoplasm originating from the surface ovarian epithelium. "These include CTSB in OAC, BAIAP2L1 in ovarian cancer and BCAR1 in a range of cancers." (PMID 28859074, 2017). "The potential contributions of LOX, BCAR1 and FAK in the malignant progression of ovarian cancer requires further investigation." (PMID 25502723, 2015).
type 2 diabetes (4 papers, 2015 to 2021). "A recent analysis suggested that the same genetic variant alters risk of both type 1 and type 2 diabetes in five regions, near CENPW, CTRB1/BCAR1, GLIS3, BCL11A and THADA." (PMID 33830302, 2021). "While BCAR1 is ubiquitous, CTRB2 code for chymotrypsinogens B2, a protease expressed exclusively in the exocrine pancreas; genetic variation therein has been previously associated with alcoholic pancreatitis and type 2 diabetes." (PMID 33517887, 2021). "For the BCAR1/CTRB1/CTRB2 region, the scores were negatively correlated (r = − 0.20), consistent with studies showing that the G allele of the rs720877 SNP in this region is associated with increased risk of type 1 diabetes but with decreased risk of type 2 diabetes." (PMID 31438962, 2019).
atherosclerosis (3 papers, 2017 to 2025). A disease characterized by the build-up of fatty material and calcium deposition in the arterial wall resulting in partial or complete occlusion of the arterial lumen. "Polymorphisms within this region have been associated with carotid intima-media thickness (i.e. a marker of subclinical atherosclerosis) and CAD risk with BCAR1 identified as the likely causal gene." (PMID 40175777, 2025). "In this study, we reviewed mechanisms of action for p130Cas/BCAR1 impact, on cardiac embryonic development defects, hypertrophy and remodeling, pulmonary artery hypertension (PAH), and atherosclerosis." (PMID 39036012, 2024). "In this review we aim to investigate the different aspects of p130Cas/BCAR1 in cardiovascular diseases from the embryogenic development level to other CVDs, including cardiac hypertrophy, myocardial remodeling, PAH, and atherosclerosis." (PMID 39036012, 2024). "BCAR1 may be affected by coxibs via other, pleiotropic mechanisms, but – like VEGFA and MMP9 – this gene has been studied functionally in the context of atherosclerosis before." (PMID 28860667, 2017).